IGF1 (insulin like growth factor 1)
Diseases named in the same sentence as IGF1 in open-access papers (continued):
Sharing a sentence is not in itself a finding about the gene and the disease.
epilepsy (continued). "However, an understanding of the pathophysiological role of reduced serum levels of BDNF and IGF-1 in patients with epilepsy requires further studies in humans." (PMID 30524358, 2018). "Serum levels of BDNF and IGF-1 in patients with epilepsy and controls." (PMID 30524358, 2018). "There was a significant decrease in serum levels of both BDNF and IGF-1 in patients with epilepsy." (PMID 30524358, 2018). "Chronic application of IGF-1 or its analogues as a treatment for brain injury may also inadvertently contribute to development of epilepsy through a similar mechanism." (PMID 27561791, 2016). "In addition, IGF-1 promotes hippocampal neurogenesis in epilepsy." (PMID 40076950, 2025). "Because IGF1 acts to increase Akt/mTOR signaling and mTOR inhibition is effective in reducing certain hallmarks of epilepsy and posttraumatic epilepsy, it is important to determine whether IGF1-based therapies for TBI increase the risk for posttraumatic epilepsy." (PMID 34095131, 2021). "In addition, patients with reduced serum levels of IGF-1 showed changes in cardiovagal function that may be related to a longer duration of epilepsy, higher seizure frequency, and temporal lobe epilepsy." (PMID 30524358, 2018). "However, the effect of IGF-1 on epilepsy remains controversial." (PMID 30524358, 2018). "The present study provides novel insights into clinical observations regarding epilepsy by showing that reduced serum levels of BDNF and IGF-1, autonomic dysfunction, and impaired cerebral autoregulation are present in patients with focal epilepsy." (PMID 30524358, 2018). "Our results indicate a possible role for BDNF and IGF-1 in regulation ANS functions and cerebral autoregulation in patients with epilepsy." (PMID 30524358, 2018). "The present study investigated the role of IGF-1 and BDNF in the regulation of autonomic functions and cerebral autoregulation in patients with epilepsy." (PMID 30524358, 2018). "The conclusion that an increase in brain size alone is insufficient to induce epilepsy is supported by the fact that seizures were not reported in IGF-1 transgenic mice despite a 55% increase in brain size." (PMID 37199581, 2023). "In the present study, we tested the hypothesis that the neurotrophic factors IGF-1 and BDNF play a crucial role in the regulation of autonomic functions and cerebral autoregulation in patients with epilepsy." (PMID 30524358, 2018). "Long-term epilepsy and severe epilepsy, particularly temporal lobe epilepsy, may perturb BDNF and IGF-1 signaling, which contribute to autonomic dysfunction and impaired cerebral autoregulation in patients with epilepsy." (PMID 30524358, 2018). "We found that cultures in all 3 groups developed epilepsy, demonstrating that externally applied IGF-1 is not necessary for development of spontaneous population spikes or ictal events." (PMID 27561791, 2016). "In a study conducted in 28 Swedish children, the Modified Atkins Diet (MAD—an alternative dietary treatment for epilepsy characterized by a low ketogenic ratio (0.8/1:1)—has been shown to induce lower levels of ketosis, which did not affect growth or IGF-1 levels at two years." (PMID 31247999, 2019). "We have no information about how IGF-1 administration would affect epilepsy in children." (PMID 28954393, 2017). "Since brain injury is associated with changes in IGF-1 signaling, and one of the downstream effectors of IGF-1 signaling, mTOR pathway, is involved in epileptogenesis, it is possible that neuroprotective levels of IGF-1 may play a role in the development of epilepsy." (PMID 27561791, 2016).
glomerulosclerosis (15 papers, 2016 to 2025). A hardening of the kidney glomerulus caused by scarring of the blood vessels. "They stated that hyperfiltration after unilateral Nx is associated with an increased filtration of IGF-1 (exposure to growth factors), which triggers glomerular expansion and leads to critical podocyte depletion, followed by proteinuria and glomerulosclerosis." (PMID 37959350, 2023). "In the IUGR animal model induced by maternal ethanol exposure, alterations in the “Glucocorticoid-insulin-like growth factor 1 (GC-IGF1) axis” programming were found to play a crucial role in impaired kidney development and susceptibility to glomerulosclerosis in adulthood." (PMID 37680850, 2023). "Excessive levels of GH were shown to induce glomerular hypertrophy and glomerulosclerosis, which may be directly caused by GH or mediated by IGF-1 (vide supra)." (PMID 34143299, 2021). "Conversely, in older recipients with lower IGF-1 levels, a smaller kidney dose, including kidneys with some glomerulosclerosis currently discarded, would be expected to have good long-term survival." (PMID 40327402, 2025). "The concept of direct GH action on glomerular cells is supported by studies in transgenic mice overexpressing human or bovine GH showing progressive glomerulosclerosis, whereas IGF-1 overexpressing mice lack glomerular changes." (PMID 34143299, 2021). "Activation of the growth hormone GH/IGF-1 axis has a direct relationship with renal hypertension, proteinuria, and glomerular sclerosis, all of which play key roles in early lesions of DKD." (PMID 27069929, 2016). "This is illustrated by murine models where overexpression of IGF-1 causes glomerular enlargement but not glomerulosclerosis, while overexpression of GH also leads to increased IGF-1, causing both glomerular enlargement and glomerulosclerosis." (PMID 40327402, 2025). "Growth hormone (GH)‐transgenic mice with permanently elevated systemic levels of GH and insulin‐like growth factor 1 (IGF1) reproducibly develop renal and glomerular hypertrophy and subsequent progressive glomerulosclerosis, finally leading to terminal renal failure." (PMID 26997624, 2016). "By contrast, transgenic mice overexpressing IGF-1 show less pronounced glomerular hypertrophy and do not develop glomerulosclerosis." (PMID 34143299, 2021). "These mice developed glomerular hypertrophy, hyperplasia, and glomerulosclerosis, similar to GH-transgenic mice with normal IGF1 expression but, in contrast to them, which did not develop proximal tubular cells hyperplasia." (PMID 34943879, 2021). "Transgenic mice overexpressing IGF1 are larger than wild-type mice, have proportionately enlarged kidneys, and also show glomerular hyperthrophy, but do not develop glomerulosclerosis." (PMID 34943879, 2021). "Transgenic animal models demonstrated that GH excess (and not IGF1) may lead to hyperfiltration, albuminuria, and glomerulosclerosis." (PMID 34943879, 2021).
Huntington disease (15 papers, 2014 to 2025). Huntington disease (HD) is a rare neurodegenerative disorder of the central nervous system characterized by unwanted choreatic movements, behavioral and psychiatric disturbances and dementia. "Conceivably, its metabolic function could be mediated by circulating leptin and adiponectin and/or IGF-1, which are perturbed by Huntington’s disease mutations in mammals." (PMID 27809764, 2016). "Recently, administration of IGF-1 has been proven to rescue Huntington’s disease phenotypes in YAC128 mice." (PMID 25140802, 2014).
leiomyoma (15 papers, 1997 to 2026). A well-circumscribed benign smooth muscle neoplasm characterized by the presence of spindle cells with cigar-shaped nuclei, interlacing fascicles, and a whorled pattern. "IGF1 was mainly expressed in fibroblasts while the IGF1 expression level in leiomyoma-associated fibroblasts was significantly higher than that in surrounding pseudocapsule." (PMID 37215998, 2023). "IGF1 was mainly expressed in fibroblasts while the IGF1 expression level in leiomyoma associated fibroblasts was significantly higher than these in surrounding pseudocapsule and normal myometrium." (PMID 37215998, 2023). "IGF-1 is one of the important factors in fibroid growth, because it is much higher than other growth factors in myometrium and leiomyoma tissues." (PMID 41514933, 2026). "Key hormonal regulator estrogen contributes to an increase in the IGF-1 gene in leiomyoma tissue." (PMID 41514933, 2026). "Insulin-like growth factor 1 (IGF-1) has been found to be overexpressed in leiomyomas." (PMID 38060710, 2023). "Under the effects of estrogen and progesterone, leiomyoma cells could promote the migration and proliferation of fibroblasts, while fibroblasts contributed to the development of leiomyoma in return via the secretion of IGF1." (PMID 37215998, 2023). "The VEGF, IGF-1, and TGF-β markers can be key biomarkers related to fibroid development and shrinkage after UAE treatment." (PMID 41514933, 2026). "The effect of VEGF on the prognosis of leiomyoma gained attention following a study demonstrating a difference in the expression of VEGF and IGF-1 after uterine artery embolization treatment." (PMID 36313223, 2022). "Importantly, in human leiomyomas, most of these signaling pathways, such as upregulation of mTOR, TGFB1 and CTNNB1 pathway, deregulation of IGF-1 signaling in human uterine leiomyoma and inflammatory process involving TNF signaling have been reported." (PMID 33244099, 2020).
medulloblastoma (15 papers, 2010 to 2025). A malignant, invasive embryonal neoplasm arising from the cerebellum. "M0 and M1 cells expressed Igf1, which has been shown to promote medulloblastoma progression, while M2 expressed Ccr2, which is associated with tumor-inhibiting macrophages." (PMID 34021242, 2021). "In our CSF samples for patients all >6mo, high risk medulloblastoma patient IGF1 levels were significantly higher than ALL patient IGF1 levels (9.56+/−4.49 versus 3.47+/−2.09, p = 0.04)." (PMID 27255663, 2016). "In contrast, Igf1-secreting microglia, which are increased in G-Smo tumors, support medulloblastoma progression." (PMID 34021242, 2021). "Progenitor-triggered medulloblastomas also contained more diverse stromal populations, with more Ccr2+ macrophages and fewer Igf1+ microglia, indicating that developmental events affected the subsequent tumor microenvironment." (PMID 34021242, 2021). "IGF1 led not only to receptor phosphorylation but also accelerated migration/adhesion in MYC amplified medulloblastoma cells in the context of appropriate matrix or meningothelial cells." (PMID 27255663, 2016). "We then extended the observation that c-MYC amplified medulloblastoma was biochemically responsive to IGF-1 stimulation in D425 cells to CHLA-01-MED cells." (PMID 27255663, 2016). "If medulloblastoma cells respond to IGF1, this would provide a “feed-forward” mechanism for tumor growth once the tumor reaches the leptomeninges." (PMID 27255663, 2016). "Based on these prior studies and the inverse correlation of MIF and CD74 in our tumor model, we propose that MIF functions in medulloblastoma to bias myeloid cells toward an Igf1+ phenotype, and acts more effectively in G-Smo tumors, which have higher Mif expression." (PMID 34021242, 2021). "In addition, IGF1/IGF1R signaling in the TME was found to be critical for medulloblastoma growth." (PMID 35688943, 2022). "To determine if this difference in Igf1 may be biologically significant, we analyzed mTORC1 activity, which is increased by IGF1 signaling and known to be important in SHH medulloblastoma progression." (PMID 34021242, 2021).
somatotroph adenomas (15 papers, 2013 to 2026). "Growth hormone-secreting pituitary adenoma (GHPA) is an insidious disease with persistent hypersecretion of GH and IGF-1, causing increased morbidity and mortality." (PMID 35019688, 2022).
thalassemia (15 papers, 2009 to 2025). An inherited blood disorder characterized by a decreased synthesis of one of the polypeptide chains that form hemoglobin. "After adjustment for BMI, age and Tanner stage, serum IGF1 concentrations correlated negatively with GDF15 in all thalassaemia patients (β = −.027, p = .02)." (PMID 36806122, 2023). "Low IGF-1 levels contributing to impaired bone health have previously been reported for HbSS and thalassemia." (PMID 25299063, 2014). "Our results suggest that GDF15 may play a role in influencing the low adiposity and low IGF1 seen in thalassaemia." (PMID 36806122, 2023). "However, it should be recognized that IGF-1 target levels might be lower than the non-ß-Thalassemia population." (PMID 35305249, 2022). "IGF1 concentration showed significant inverse correlations with GDF15 concentration (adjusted for BMI, age, sex and Tanner stage) in both the All Thalassaemia and the Thalassaemia Major groups." (PMID 36806122, 2023).
bipolar disorder (14 papers, 2014 to 2025). A disorder of the brain that causes unusual shifts in mood, energy, activity levels and the ability to carry out day-to-day tasks. "There is further an interesting theoretical connection between GH and the circadian rhythm dysfunction associated with bipolar disorder through the suggested crosstalk between the GH/insulin-like growth factor 1 (IGF-1) axis and the circadian clock system." (PMID 35986174, 2022). "In addition, the polymorphism occuring in IGF-1 gene may have an important role in the emergence of bipolar disorder." (PMID 32283906, 2020). "It has been reported that plasma IGF-1 concentrations are increased in acute depressed patients and similarly, another study demonstrated that patients with bipolar disorder have elevated IGF-1 concentrations." (PMID 25734326, 2015). "The changes in the levels of GDNF, IGF-1 and Nrn 1 might be involved in pathopysiology of bipolar disorder, and GDNF, IGF-1 may be considered as state markers in bipolar manic episode." (PMID 32283906, 2020). "Hovewer, GDNF and IGF-1 may be used as state markers and these findings will be helpful for the development of new treatment strategies which include neurotrophins for bipolar disorder in the future." (PMID 32283906, 2020). "Factors such as fibroblast growth factor (FGF)-2, vascular endothelial growth factor (VEGF), nerve growth factor (NGF), and insulin-like growth factor (IGF)-1 might be potential candidate biomarkers for bipolar disorder." (PMID 31118905, 2019). "However, further investigations on the correlation between cognitive function and peripheral IGF-1 levels are needed to explore the role of IGF-1 in the pathophysiology of major affective disorders." (PMID 26825882, 2016). "In addition, IGF-1 can mediate an antidepressant effect in patients with major affective disorder, and its levels in the cerebrospinal fluid have been found to vary with antidepressant treatment." (PMID 26825882, 2016). "Role of IGF-1 inhibitor in bipolar disorder may be worth looking into." (PMID 35672318, 2022). "In a meta-analysis for patients with MDD and bipolar disorder, as well as a meta-analysis of patients with MDD, serum IGF1 levels were higher and serum DHEAS levels were lower in patients than in controls." (PMID 33731067, 2021). "Investigating the relationship between peripheral IGF-1 and growth hormone levels would have provided further information on the role of IGF-1 in the pathophysiology of major affective disorders." (PMID 26825882, 2016). "One study found higher IGF-1 and slightly lower GH (not statistically significant) in serum from bipolar disorder patients compared with controls." (PMID 35986174, 2022). "In patient-derived lymphoblastoid cell lines, bipolar disorder patients who respond to lithium have higher levels of IGF1 than bipolar disorder patients who do not respond to lithium." (PMID 24672476, 2014). "Interestingly, several studies have found increased peripheral IGF-1—a negative feedback regulator of GH gene expression —in patients with bipolar disorder." (PMID 35986174, 2022). "However, increased peripheral IGF-1 levels in bipolar disorder may be related with the absence of negative feedback resulting from the reduced central effect of IGF-1." (PMID 32283906, 2020).
cystic fibrosis (14 papers, 2009 to 2024). Autosomal recessive disorder caused by pathogenic variants in the CFTR gene (cystic fibrosis transmembrane conductance regulator), which encodes a chloride and bicarbonate channel expressed in epithelial cells, and follow the diagnosis criteria. "IGF-1 levels are closely linked to body fat and BMI and recognised to be low in children with chronic illness such as cystic fibrosis, cyanotic congenital heart disease or short bowel syndrome." (PMID 37386483, 2023). "Low levels of insulin-like growth factor 1 (IGF-1) have been observed in the serum of cystic fibrosis patients." (PMID 23555857, 2013). "Thus, it is possible that an additive treatment combining IGF-1 with a corrector would be more effective for cystic fibrosis than a corrector alone." (PMID 23555857, 2013). "To determine whether this regulation occurs in bronchial epithelial cells from cystic fibrosis patients (CFBE41o-, referred to as CFBE), we treated CFBE-WTCFTR cells (CFBE cells stably transfected with CFTR) with IGF-1." (PMID 23555857, 2013). "Our results also indicate that that IGF-1 selectively increases CFTR protein expression and CFTR-mediated chloride transport in a cell line model, CFBE cells (the bronchial epithelial cell line from cystic fibrosis patients)." (PMID 23555857, 2013). "However, the effects of low serum IGF-1 on the cystic fibrosis transmembrane conductance regulator (CFTR), whose defective function is the primary cause of cystic fibrosis, have not been studied." (PMID 23555857, 2013).
multiple sclerosis (14 papers, 2013 to 2024). A progressive autoimmune disorder affecting the central nervous system resulting in demyelination. "We used the established animal model of multiple sclerosis to screen out a profile of the GH/IGF-1 axis in female EAE rats." (PMID 38892024, 2024). "IGF-1 is considered a potential therapeutic agent for the treatment of several CNS pathologies including multiple sclerosis (MS)." (PMID 36890580, 2023). "While after traumatic brain injury (TBI) the endogenous IGF-1 level has been shown to increase, in multiple sclerosis (MS), which is one of the most deeply studied demyelinating diseases, a local deficiency of this growth factor has been observed, often within the areas of demyelination." (PMID 32691304, 2020). "The effects of IGF-1 have also been tested in different models for multiple sclerosis." (PMID 25339185, 2014). "To establish a broader role for IGF-1 in restoring immune tolerance, we exploited a murine model of multiple sclerosis, a chronic autoimmune demyelinating disease of unknown etiology." (PMID 25339185, 2014). "In neuroinflammatory conditions including multiple sclerosis (MS) and its animal model experimental autoimmune encephalomyelitis (EAE), IGF-1 can regulate cellular survival and activation in a context-dependent and cell-specific manner." (PMID 36890580, 2023). "In contrast, it has been reported that combination of bpV(phen) and insulin-like growth factor-1 (IGF-1) promotes myelination in rat and human OLG progenitors cultures, suggesting a potential therapeutic application of bpV(phen) in multiple sclerosis (MS)." (PMID 29385737, 2018). "Moreover, administration of IGF-1 to a small cohort of multiple sclerosis patients did not alter clinical disease activity." (PMID 23650566, 2013).